EHD2 (EH domain containing 2)
Diseases named in the same sentence as EHD2 in open-access papers (continued):
Sharing a sentence is not in itself a finding about the gene and the disease.
tumor (17 papers, 2013 to 2025). "Significant associations were found between EHD2 and tumor grade, ER status, PR status, HER2 status and proliferation using Ki67 in this cohort of 421 patients." (PMID 32409676, 2020). "Disorder of EHD2 expression in tumor tissue may cause esophageal squamous cell structure to change and obtain the migration ability." (PMID 23354948, 2013). "Studies have shown that hypoxia can activate the HIF-1 pathway and EH domain-containing protein 2 (EHD2), leading to the initiation of macropinocytosis in tumor cells and their increased growth." (PMID 38533500, 2024). "(G, H) Representative IHC staining of tumor sections for EHD2 (G) or Ki67 (H), with respective controls." (PMID 36625722, 2023). "When orthotopically implanted in nude mice, EHD2-KO MDA-MB-231 cells exhibited a marked and significant defect in tumor formation, with a significant rescue upon mouse Ehd2 expression." (PMID 36625722, 2023). "In vivo, loss of EHD2 markedly impaired the orthotopic TNBC xenograft formation and metastasis, and tumor growth was rescued by exogenous mouse Ehd2." (PMID 36625722, 2023). "Orthotopically implanted control Hs578T cells produced xenograft tumors over time while EHD2 KD cells showed a severe reduction in tumor formation." (PMID 36625722, 2023). "Our results differ from reports that reduction in EHD2 expression correlates with tumor progression in BC." (PMID 36625722, 2023). "Immunostaining confirmed the EHD2 KD and showed marked reduction in proliferation (Ki67+) with sparse tumor cells in H&E sections." (PMID 36625722, 2023). "Clinicopathological analysis further demonstrated that EHD2 overexpression was significantly correlated with a large tumor size in human HCC patients." (PMID 35177645, 2022). "KO of EHD2 in MHCC97L cells dramatically suppressed HCC tumor growth, lung metastasis, and macropinocytosis." (PMID 35177645, 2022). "Altogether, our study not only reveals that EHD2 acts as a tumor suppressor, it is also a new independent prognostic factor of metastasis-free survival and a new biomarker of chemotherapy response in TNBC patients." (PMID 32409676, 2020). "In these cancers, EHD2 gene has been suggested to be a tumor suppressor gene involved in carcinogenesis, tumor cell migration and invasion." (PMID 28358874, 2017). "This is in line with previous findings for EGFR-targeting diabody-scTRAIL fusion proteins (Db-scTRAIL) and dimeric EHD2-scTRAIL fusion proteins, all exhibiting very strong tumor cell killing activity with subnanomolar EC50values, although different pharmacokinetic properties." (PMID 40328809, 2025). "Decreased EHD2 expression correlates with higher tumor grade and metastasis rates, suggesting that EHD4 may play a role in HCC through a similar mechanism." (PMID 40564032, 2025). "Bottom, representative tumor sections stained for EHD2 and control." (PMID 36625722, 2023). "Immunostaining showed that EHD2 had a cytoplasmic and membranous staining pattern in tumor cells." (PMID 28358874, 2017). "We further repeated EHD2 immunostaining on whole tissue sections to investigate whether dyscohesive cells in the tumor periphery and invasive front expressed EHD2 protein." (PMID 28358874, 2017). "Further research of the mechanism how EHD2 potential regulates the cytoskeleton molecular will broaden the understanding of the tumor moleculars and cell biology, which may provide a new target and new ideas for the diagnosis and treatment for ESCC." (PMID 23354948, 2013). "Therefore, further studies are needed to investigate whether EHD2 expression is functionally essential for the development of dyscohesive cells in the tumor periphery and invasive front." (PMID 28358874, 2017). "The role of EHD2 expression may have different implications in different types of tumor." (PMID 28358874, 2017). "We speculated that under-expression of EHD2 reduced chemosensitivity in tumor cells." (PMID 23354948, 2013).
tumor (continued). "A recent study found that, through the HIF/EHD2 pathway, hypoxia induces extensive HCC cell MPC, allowing the tumor to acquire exocytic nutrients and prolong survival." (PMID 37064147, 2023). "Seven hub genes (AXL, EFEMP2, VIM, EHD2, FSTL3, ALOX5, HSPB8) were downregulated in tumor samples, while COL3A1 was upregulated in tumor samples in the TCGA dataset." (PMID 37291533, 2023). "Lastly, the EHD2, CTIF, FBXO32, PIP5K1C, and AHNAK genes were found to be co-expressed in the adjacent healthy tissue and tumor tissue groups." (PMID 37365287, 2023). "We found that the expression levels of EFEMP2, EHD2, FSTL3 and ALOX5 were decreased in tumor tissues, whereas COL3A1 was significantly increased in tumor samples." (PMID 37291533, 2023). "Other proteins were inversely correlated to tumor tissue content, the most significant being; TENX, EHD2, ZA2G, AOC3, FETUA and THRB." (PMID 28445515, 2017). "After interference of EHD2, the ESCC cell line TE1 accelerated cell growth speed which further supported a potential assumption that EHD2 was a tumor suppressor of ESCC." (PMID 23354948, 2013). "There was a strong negative correlation between KIF5A mRNA expression and tumour grade, and a strong positive correlation between EHD2 expression and grade." (PMID 38638676, 2024). "Corresponding m/z from collagen type I alpha 2 (COL1A2), cathepsin (CTSG), elongation factor 1-alpha 1 (EEF1A1), EH domain-containing protein 2 (EHD2), epiplakin 1 (EPPK1), prelamin-A/C (LMNA), and prolargin (PRELP) showed higher intensity distribution in HND in comparison to LND tumour areas." (PMID 40603632, 2024). "We observed a negative correlation between EHD2 expression and tumor aggressiveness, especially in TNBC patients." (PMID 32409676, 2020). "Thus, our findings support a model whereby EHD2-dependent stabilization of cell surface caveolae ensures high cell surface levels of Orai1 to enable robust SOCE in TNBCs, which in turn promotes pro-tumorigenic and pro-metastatic behaviors of tumor cells." (PMID 36625722, 2023). "Importantly, EHD2 expression was not changed in the stromal cells surrounding the tumor." (PMID 32409676, 2020). "Accordingly, we show that SKF96365 treatment significantly reduced the control TNBC xenograft tumor growth; we were unable to test the SOCE inhibitor against EHD2-KO TNBC xenografts as these did not grow sufficiently to test the inhibitor impact." (PMID 36625722, 2023).
cancer (7 papers, 2012 to 2023). A tumor composed of atypical neoplastic, often pleomorphic cells that invade other tissues. "EHD2 has recently been associated with several human cancers, however the significance of EHD2 transcript levels in cancer prognosis remains debated." (PMID 32409676, 2020). "EHD2 has recently been associated with several types of cancer." (PMID 32409676, 2020). "We identified the precise mechanism by which the HIF/EHD2 pathway supports macropinocytosis-mediated metabolic reprogramming in cancer, providing an important molecular basis for the design of innovative cancer-therapeutic strategies against macropinocytosis." (PMID 35177645, 2022). "Further studies will be required to better understand the role that EHD2 plays in various cancer types." (PMID 32409676, 2020). "Generally, our results demonstrated that EHD2 expression in the cancer with lymph nodes metastases decreased significantly, which indicated that under-expression of EHD2 had a potential relation with the severity of malignancy of ESCC." (PMID 23354948, 2013). "Recent studies have painted a complex picture of the potential roles of EHD2 in cancer." (PMID 36625722, 2023). "Furthermore, we show that HIF-1 induces the transcription of EHD2, driving actin-dependent membrane-ruffle formation and macropinocytosis in hypoxic cancer cells." (PMID 35177645, 2022). "This new correlation between EHD2 and IL-8 levels may explain the anti-metastatic role of EHD2 in cancer." (PMID 32409676, 2020). "Our study is therefore the first one to report that the regulation of IL-8 may be regulated by EHD2, suggesting that EHD2 could be a potential target to inhibit the IL-8 pathway and cancer stem cell activity." (PMID 32409676, 2020). "EHD2 has recently drawn attention to its potential role in cancer development." (PMID 32409676, 2020). "The study found that the expression level of EHD2 was significantly lower than that of normal tissue, and EHD2 expression gradually decreased with pathological grading increased, which indicating EHD2 might be a cancer suppressor gene of ESCC." (PMID 23354948, 2013). "Our studies suggest a novel pro-oncogenic mechanism of EHD2, namely its requirement for efficient store-operated calcium entry (SOCE), a pathway known to promote tumorigenesis and metastasis in breast and other cancers." (PMID 36625722, 2023). "As macropinocytosis provides an alternative fuel to cancer cells during nutrient limitation, it is not surprising that a relatively prominent effect of EHD2 could be observed in vivo." (PMID 35177645, 2022).
central nervous system diseases (1 paper, 2018). "The function of Ehd2 in central nervous system diseases is still incomplete." (PMID 29487848, 2018).
EHD2 also shares sentences with these, for which no sentence is quoted: papillary thyroid carcinoma (2 papers); astrocytoma (1); Insulin resistance (1); intrahepatic cholangiocarcinoma (1); liver cirrhosis (1); metastatic tumors (1); oligodendroglioma (1); ovarian carcinoma (1); serous ovarian cancers (1); Stroke (1).